DCDC2 (doublecortin domain containing 2)
Diseases named in the same sentence as DCDC2 in open-access papers (continued):
Sharing a sentence is not in itself a finding about the gene and the disease.
dyslexia (continued). "Despite early findings that DCDC2 is a strong candidate for developmental dyslexia and that some of the genetic variants have been linked to brain structure and functions, our findings showed that DCDC2 is not strongly associated with dyslexia." (PMID 29081827, 2017). "In addition to dyslexia, DCDC2 has also been reported to contribute to reading abilities in the general population." (PMID 27100778, 2016). "From those genes, DYX1C1, KIAA0319 and DCDC2 are the most prominent candidate genes for dyslexia." (PMID 27312598, 2016). "DCDC2 was the first dyslexia protein shown to regulate ciliary signalling." (PMID 23650548, 2013). "Four genes associated with dyslexia in particular are involved in the development of the cerebral neocortex, either in terms of axonal guidance (ROBO1) or neuronal migration (KIAA0319, DCDC2, and DYX1C1)." (PMID 22606227, 2012). "We identified association between reading abilities and the DCDC2, KIAA0319, and CMIP genes and have shown that these associations follow different patterns; whereas DCDC2 is associated more specifically with dyslexia, CMIP and KIAA0319 are associated with reading abilities in the normal range." (PMID 21457949, 2011). "DCDC2, DYX1C1, and KIAA0319 may be pathogenic genes that contribute to dyslexia." (PMID 37667328, 2023). "To date, several risk loci and four candidate genes have been identified for dyslexia [DXY1C1, KIAA0319, DCDC2 and ROBO1—], all of which are strongly implicated in neural migration during development, suggesting that dyslexics brain may present altered connections between brain areas." (PMID 34228165, 2021). "While it remains possible that cilia could mediate neuronal migration, it is interesting to note that, for the patients with ciliopathies carrying DYX1C1 and DCDC2 mutations, symptoms of dyslexia or other cognitive problems have not been reported." (PMID 30218584, 2018). "This could be due to heterogeneity of samples of dyslexia due to different genes responsible for the phenotype or other involvement of unknown gene-environment interactions or some other transcriptional regulatory factors of DCDC2." (PMID 29081827, 2017). "Our results do not reveal a migration disorder in the mouse model, adding to the body of evidence available for Dcdc2 and Dyx1c1 that, unlike in the rat in utero knockdown models, the dyslexia-susceptibility candidate mouse homolog genes do not play an evident role in neuronal migration." (PMID 27510895, 2017). "Therefore, on the basis of multiple strands of evidence, we conclude that the DCDC2 deletion is not a strong risk factor for dyslexia." (PMID 28742079, 2017). "Thus, it is reasonable to hypothesize that genes associated with dyslexia and migrational error in animal models, such as KIAA0319 and DCDC2, contribute to orbitofrontal and superior temporal sulcus findings in people with reading disability." (PMID 26835509, 2016). "We did not observe association of DCDC2 alleles with dyslexia in our multigenerational US sample, although there was a slight tendency for the intronic deletion to be associated with worse performance on some quantitative measures of dyslexia in the probands, but not in their parents." (PMID 23308072, 2012). "Therefore, it has been speculated that the effect of abnormal DCDC2 in dyslexia might be mediated through disruption of microtubule-mediated movement of proteins and cell migration." (PMID 23308072, 2012). "DCDC2 and KIAA0319 are present on 6p22, previously reported for dyslexia and childhood apraxia of speech (CAS)." (PMID 39202429, 2024). "The most frequently replicated locus is DYX2 on chromosome 6p21.3, and the most frequently replicated dyslexia genes on DYX2 are KIAA0319 and DCDC2." (PMID 36016658, 2022). "K1AA0319 is also responsible for the development of Dyslexia, and it functions with DCDC2 because the evidence states that there is a gene–gene interaction between K1AA0319 and DCDC2." (PMID 34674647, 2021).
dyslexia (continued). "In fact, several reports have demonstrated that many dyslexia candidate genes, such as DYX1C1 and DCDC2, have a reported structural or functional role in cilia." (PMID 34068951, 2021). "Since a German group has found some interactions between DCDC2 and KIAA0319 in a large German dyslexia sample, we also attempted to find similar interactions." (PMID 29081827, 2017). "Dyslexia is highly heritable and at least four candidate-dyslexia genes have been identified (KIAA0319, DYX1C1, DCDC2 and ROBO1)." (PMID 24871331, 2014). "It is interesting to note that all four of the best characterized candidate-dyslexia genes (KIAA0319, ROBO1, DYX1C1, and DCDC2) interfere with auditory processing." (PMID 24871331, 2014). "Our group has already published on candidate dyslexia genes KIAA0319, DYX1C1 and DCDC2 based on targeted genotyping of regions in a smaller dataset than is used here." (PMID 23738518, 2013). "With direct evidence implicating now DYX1C1 and DCDC2 in ciliary functions and the bioinformatic suggestion of a role for KIAA0319 as well, we propose that dyslexia should become considered as a new type of ciliopathy." (PMID 23650548, 2013). "Within the three most-replicated dyslexia loci, four candidate genes for dyslexia have been identified: DYX1C1 in DYX1 on chromosome 15q21, DCDC2 and KIAA0319 in DYX2 on chromosome 6p21, and ROBO1 in DYX5 on chromosome 3p12–q12." (PMID 23308072, 2012). "The novel findings included a set of genes (DCDC2, DYX1C1, KIAA0319) related to a neurological disease dyslexia suggesting their potential involvement in ciliary functions." (PMID 22558177, 2012). "Two of the most replicated dyslexia candidate genes are DYX1C1 (DNAAF4) and DCDC2." (PMID 37237337, 2023). "The present study considers a sample of adolescents with dyslexia with and without the intron 2 deletion on the DCDC2 gene." (PMID 34228165, 2021). "Dyslexia candidate genes have been correlated with tasks measuring phonological abilities, such as DYX1C1 and FOXP2 with short-term memory or phonological memory, or DCDC2 and KIAA0319 with phoneme awareness itself." (PMID 30379906, 2018). "Here we explored whether variations within three related-dyslexia genes, namely KIAA0319, DCDC2, and CNTNAP, might affect cortical thickness measures in FTD patients." (PMID 27484312, 2016). "Moreover, as reviewed in a recent study, the dyslexia candidate genes including KIAA0319, doublecortin domain containing 2 (DCDC2) and roundabout homolog 1 (ROBO1) are candidate genes involved in speech sound disorder (SSD) as well." (PMID 25178928, 2014). "We examined 4 SNPs located on genes previously associated to dyslexia (KIAA0319, DCDC2, DYX1C1 and FOXP2) and 3 SNPs within genes related to ADHD (COMT, MAOA and DBH) in a cohort of Spanish children (N = 2078) that met the criteria of having one, both or none of these disorders (dyslexia and ADHD)." (PMID 30379906, 2018).
ciliopathy (8 papers, 2013 to 2023). "An increasing usage of NGS technology has also enabled the discovery of new causal genes in ciliopathies, including the DCDC2 gene." (PMID 37296768, 2023). "DCDC2 has recently been implicated in renal-hepatic ciliopathy, and histological changes consistent with the human phenotype have also been detected in the Dcdc2 knockout mouse." (PMID 27510895, 2017). "The main clinical presentation of DCDC2-related ciliopathy is liver disease in the form of neonatal sclerosing cholangitis." (PMID 37296768, 2023). "Genetic analysis is a powerful approach to revealing genetic interactions between two genes, and our genetic analysis helps us to uncover a novel genetic interaction between two ciliopathy disease genes (RPI-1/DCDC2 and NPHP-4/NPHP4) in C. elegans." (PMID 37529113, 2023). "A total number of 28 patients (from 24 families) affected with DCDC2-related ciliopathy were identified." (PMID 37296768, 2023). "The main clinical presentation of DCDC2-related ciliopathy was liver disease in the form of neonatal sclerosing cholangitis." (PMID 37296768, 2023). "Based on our case series and the literature review, we conclude that the main clinical presentation of DCDC2-related ciliopathy is liver disease in the form of NSC." (PMID 37296768, 2023). "Taken together, our analysis discovered a novel genetic interaction between two ciliopathy disease genes (RPI-1/DCDC2 and NPHP-4/NPHP4) in C. elegans." (PMID 37529113, 2023). "Conversely, we are unaware whether patients with such ciliopathies, caused by DYX1C1 and DCDC2 mutations, show symptoms of SLD or other cognitive impairments." (PMID 34068951, 2021). "The predominance of early and severe liver disease associated with no or mildly expressed kidney involvement is observed in DCDC2-related ciliopathy." (PMID 37296768, 2023). "The characteristic phenomenon with predominance of early and severe liver disease associated with no or mildly expressed kidney involvement in DCDC2-related ciliopathy needs to be fully elucidated." (PMID 37296768, 2023).
deafness (7 papers, 2015 to 2023). An inherited or acquired condition characterized by the complete loss of the ability to hear from one or both ears. "Abnormalities in cilia structure and function were also seen in association with Dcdc2 dysregulation, and a missense mutation in DCDC2 is known to cause deafness in humans, likely associated with cochlear cilia abnormalities." (PMID 36452335, 2022). "The gene DCDC2 (Doublecortin domain containing 2a, Dcdc2a) underlies human recessive deafness DFNB66." (PMID 31927188, 2020). "DCDC2 localizes to cilia, and has been implicated in both autosomal (dominant or recessive) human kidney disease and autosomal recessive deafness." (PMID 28866788, 2017).
schizophrenia (4 papers, 2014 to 2023). A major psychotic disorder characterized by abnormalities in the perception or expression of reality. "DCDC2 gene is located on chromosome 6p22.1, a region with strong evidence of linkage with schizophrenia." (PMID 25206360, 2014). "We identified a number of genes with significant epigenetic alterations in schizophrenia, and some of these genes, such as GRIA4, ASTN2, and DCDC2 (doublecortin domain containing 2) with increased DNA methylation at particular CpG loci, have previously been implicated in schizophrenia." (PMID 25206360, 2014). "Moreover, a linkage between DCDC2 SNPs and gray matter volumes in the superior prefrontal, temporal, and occipital networks (regions including multiple reading and language-related areas), has been found; linkages were observed in subjects with schizophrenia, but not in the control group." (PMID 28125008, 2017).
cholestasis (3 papers, 2021 to 2023). Impairment of the bile flow caused by obstruction within the liver, or outside the liver in the bile duct system. "Besides cholestasis, the main characteristic feature of DCDC2 deficiency is biliary-tract inflammation with scarring." (PMID 37296768, 2023).
colorectal cancer (3 papers, 2023 to 2025). A primary or metastatic malignant neoplasm that affects the colon or rectum. "Recently, it was discovered that DCDC2 plays a role in the progression of colorectal cancer by interacting with DVL2 to regulate the Wnt pathway." (PMID 40533767, 2025). "To verify the effects of the DCDC2 protein in colorectal cancer, we transfected DCDC2 expression plasmids into HCT116 cells." (PMID 36739270, 2023). "Additionally, recent studies have increasingly demonstrated the involvement of DCDC2 in the occurrence and development of various malignant tumors, including ovarian cancer, breast cancer, prostate cancer, colorectal cancer, and HCC27,49–52." (PMID 38658618, 2024).
language disorder (3 papers, 2011 to 2023). A category of disorders characterized by an impairment in the development of an individual's language capabilities, which is in contrast to his/her non-verbal intellect. "We provide further support for the role of KIAA0319 and DCDC2 in contributing to reading abilities and novel evidence that the language-disorder candidate gene CMIP is also implicated in reading processes." (PMID 21457949, 2011).
primary ciliary dyskinesia (3 papers, 2014 to 2023). A rare, genetically heterogeneous, primarily respiratory disorder characterized by chronic upper and lower respiratory tract disease. "Dcdc2 has been implicated in the control of cilia length, and disruption of Dyx1c1 in mice and zebrafish leads to laterality defects and impairments in cilia function, resembling that observed in primary ciliary dyskinesia (PCD)." (PMID 24705331, 2014). "Mutations in DYX1C1 cause primary ciliary dyskinesia (PCD) and loss-of function mutations in DCDC2 can cause a wide spectrum of cilia-related disorders such as nephronophthisis-related ciliopathies (NPHP-RC), hereditary hearing loss, and neonatal sclerosing cholangitis." (PMID 37237337, 2023).
Alagille syndrome (2 papers, 2022). "However, the obstructive characteristics develop in a time-dependent manner and also occur in Alagille syndrome, A1ATd, cystic fibrosis, parenteral nutrition-associated NC (PNALD), PFIC3, and isolated neonatal sclerosing cholangitis (gene DCDC2)." (PMID 36292464, 2022). "Could single-gene analysis for JAG1, NOTCH2 (Alagille syndrome), SERPINA 1(A1ATd), DCDC2 (isolated neonatal sclerosing cholangitis), and ABCB4 (PFIC3) still be used to exclude these intrahepatic diseases and avoid diagnostic errors in the first step of the investigation?" (PMID 36292464, 2022).
Hepatic fibrosis (2 papers, 2017 to 2024). The presence of excessive fibrous connective tissue in the liver. "As a member of the doublecortin domain-containing family, doublecortin domain containing 2 (DCDC2) mutations can lead to neonatal sclerosing cholangitis, but its involvement in liver fibrosis remains unclear." (PMID 38658618, 2024). "Immunochemistry analysis revealed that patients with liver fibrosis exhibited decreased tissue expression of DCDC2 compared to the control groups." (PMID 38658618, 2024). "To investigate the expression levels of DCDC2 in liver fibrosis, we obtained tissue samples from healthy individuals as well as those with liver fibrosis." (PMID 38658618, 2024). "Our initial findings revealed a significant down-regulation of DCDC2 expression, both at the protein and mRNA levels, in human and mouse liver fibrosis models compared to their respective normal counterparts." (PMID 38658618, 2024). "Our analysis revealed a down-regulation of both RNA and protein levels of DCDC2 in the human liver fibrosis group, accompanied by increased levels of α-SMA and Col1α1." (PMID 38658618, 2024). "To confirm the effect of DCDC2 in liver fibrosis, we collected human normal liver tissues and liver fibrosis tissues." (PMID 38658618, 2024). "Finally, we demonstrated that injecting lentivirus into the tail vein, which delivered DCDC2 expression to the liver, effectively improved liver fibrosis." (PMID 38658618, 2024). "The levels of DCDC2 mRNA and protein were significantly reduced in the liver fibrosis groups." (PMID 38658618, 2024). "It interacts with DVL, and DCDC2 knockdown leads to defects in Wnt signaling and may contribute to the liver fibrosis." (PMID 29379777, 2017). "In vivo, exogenous DCDC2 could ameliorate CCl4-induced liver fibrosis." (PMID 38658618, 2024). "Therefore, this study aims to elucidate the role of DCDC2 in liver fibrosis." (PMID 38658618, 2024). "DCDC2 inhibited the activation of HSC induced by TGF-β1 in vitro and fibrogenic changes in vivo, suggesting that it is a promising therapeutic target for liver fibrosis and warrants further investigation in clinical practice." (PMID 38658618, 2024). "In conclusion, DCDC2 exhibited a significant downregulation in TGF-β1-activated HSC and CCl4-induced liver fibrosis in mice." (PMID 38658618, 2024). "However, to date, no studies have explored the potential relationship between DCDC2 and liver fibrosis." (PMID 38658618, 2024). "However, the specific role of DCDC2 in HSC activation and liver fibrosis remains unexplored." (PMID 38658618, 2024).
liver disease (2 papers, 2023). "Neonatal sclerosing cholangitis (NSC) is a rare and severe autosomal recessive inherited liver disease with mutations in DCDC2, commonly requiring liver transplantation (LT) for decompensated biliary cirrhosis in childhood." (PMID 36816379, 2023). "NSC is a rare hereditary liver disease in nurseling, for which DCDC2 mutation was mainly responsible." (PMID 36816379, 2023). "Author Summary: Neonatal sclerosing cholangitis (NSC) is an uncommon and severe inherited liver disease, which mutations in DCDC2 are responsible for, often leading to liver transplantation (LT) for end-stage liver disease in childhood." (PMID 36816379, 2023). "Since then, more and more patients with isolated liver disease (normal kidney function) or combined liver and kidney disease associated with DCDC2 pathogenic variants have been described." (PMID 37296768, 2023). "In recent years, more and more patients with isolated liver disease or combined liver and kidney disease associated with DCDC2 pathogenic variants have been described." (PMID 37296768, 2023).
nephronophthisis (2 papers, 2020 to 2023). Progressive tubulointerstitial injury, inherited in an autosomal recessive pattern, caused by mutations in genes involved in ciliary function, which may result in an end stage renal failure. "DCDC2 in the context of kidney diseases is linked to renal ciliopathies and nephronophthisis; however, insulin signalling is not directly linked to these disorders." (PMID 33458251, 2020).
ovarian carcinoma (2 papers, 2022 to 2024). A malignant neoplasm originating from the surface ovarian epithelium. "In taxol-resistant ovarian cancer cells, NEB along with DCDC2, ANKRD18B, ALDH1A1, and ITGBL1 were overexpressed suggesting the involvement of these AR-related genes in taxol resistance." (PMID 35975176, 2022).
type 2 diabetes (2 papers, 2021 to 2025). "According to the literature study, some genes that are associated with developmental dyslexia, such as ROBO1, DCDC2, DYX1C1, and KIA0319, and some genes that are associated with type 2 diabetes CTNNB1, TCF7L2, and KIF3A had shown some connections with each other." (PMID 34674647, 2021).
autoimmune disease (1 paper, 2025). A disorder resulting from loss of function or tissue destruction of an organ or multiple organs, arising from humoral or cellular immune responses of the individual to their own tissue constituents. "Although DCDC2 is primarily associated with neuronal development, recent research has linked its polymorphisms to susceptibility to autoimmune diseases, potentially influencing immune system function through neuro-immune axis crosstalk." (PMID 40777016, 2025).
cholelithiasis (1 paper, 2025). The presence of crystallized deposits forming in the gallbladder or biliary tree, primarily composed of cholesterol, bilirubin, and bile. "Moreover, the existence of DCDC2 autoantibody was examined in Fudan cohort-III, consisted of the serum from healthy donors (HD), patients with cholelithiasis (CLS), with gallbladder cancer (GBC), with ECC, or with ICC." (PMID 40533767, 2025).
colon cancer (1 paper, 2025). "Similarly, suppression of DCDC2 expression led to inhibition of cell proliferation and subsequent metastasis in colon cancer." (PMID 40871563, 2025).
colorectal tumor (1 paper, 2023). "CCK-8 and transwell assays confirmed that DCDC2 promoted colorectal tumor cell proliferation and metastasis." (PMID 36739270, 2023).
cyst (1 paper, 2021). A sac-like closed membranous structure that may be empty or contain fluid or amorphous material. "Knockdown of DCDC2/NPHP19 has been shown to activate the canonical Wnt pathway and cause pronephric cyst formation in zebrafish, a phenotype which could be rescued by a β-catenin inhibitor." (PMID 34055783, 2021).